AR (androgen receptor)
Diseases named in the same sentence as AR in open-access papers (continued):
Sharing a sentence is not in itself a finding about the gene and the disease.
ovarian carcinoma (continued). "Clearly, these findings reveal an important role for androgen/AR signaling in stimulating the growth and/or progression of ovarian cancers." (PMID 27741511, 2017). "We found that AR overexpression indeed promoted proliferation and migration of these ovarian cancer cell lines as determined by MTT proliferation and transwell migration assays." (PMID 27741511, 2017). "Here, we summarize current findings regarding the role of the AR in ovarian cancer and discuss agents that target this pathway as potential therapeutics for ovarian cancer." (PMID 27741511, 2017). "It is well established that androgen receptors (AR) are commonly expressed in epithelial ovarian cancer, and novel agents targeting the AR signaling pathway are being investigated in this disease." (PMID 28666422, 2017). "AR is expressed in a majority of human ovarian cancers and androgen/AR signaling stimulates proliferation, cell migration and invasion of ovarian cancer cells." (PMID 27741511, 2017). "Therapeutic targeting of AR has been employed since the 1990s; however, only a limited number of clinical trials have assessed the efficacy of anti-androgens in ovarian cancers so far." (PMID 27741511, 2017). "Given the tumor-promoting role of AR, several other studies evaluated the potential prognostic value of AR in ovarian cancer patients." (PMID 27741511, 2017). "Further studies showed AR expression was detected in about 90% of epithelial ovarian cancers by biochemical receptor assay and 43.5-86% by immunohistochemistry." (PMID 27741511, 2017). "Evidence has shown that androgen receptor is involved in the pathogenesis of ovarian cancer, and clinical trials using anti-androgens showed a response in relapsed ovarian cancer." (PMID 27275818, 2016). "Here, We aim to evaluate the relationship between AR CAG and GGN repeat length polymorphisms and Epithelial Ovarian Cancer (EOC) risk in a two-stage, case-control study among Chinese women." (PMID 26556855, 2016). "Epidemiologic and biological data suggest a role for androgens and androgen receptor (AR) in ovarian cancer development." (PMID 26556855, 2016). "On the other hand, a relationship between the androgen receptor (AR) and TGF-β1 receptor expression has been demonstrated in ovarian cancer; however, the underlying mechanism is incompletely understood." (PMID 26091707, 2016). "Although the AR is expressed in both normal and cancerous ovaries, we possess a limited understanding of AR activity in ovarian cancer cells." (PMID 26318424, 2015). "Epidemiological evidence and laboratory data strongly support a critical role for androgens in the origin and promotion of epithelial ovarian cancer and have led to clinical trials designed to target the AR." (PMID 26318424, 2015). "A DNA microarray analysis revealed over 120 AR-upregulated genes in OVCAR3 ovarian cancer cells, with the majority being related to transcription, proliferation, and G-protein signaling." (PMID 26318424, 2015). "Identification of AR as a driver for stimulating drug resistance genes in ovarian cancers, as demonstrated in this study, should improve our understanding of taxol sensitivity and resistance in ovarian cancer." (PMID 26318424, 2015). "Since ABCB1 has been shown to represent an important factor for multiple drug resistance, the finding that the FKBP5/AR/ABCB1 axis plays a role in txr in ovarian cancer cells supports the usefulness of our strategy." (PMID 25460502, 2014). "Our findings suggest that mitotoxin-based treatment against ovarian cancer should be avoided when the Akt/FKBP5/AR axis is activated." (PMID 25460502, 2014).
ovarian carcinoma (continued). "Steroid hormone receptors, such as ER, progesterone receptor (PR), and AR, are involved in the development of endocrine organ cancers, including ovarian cancer." (PMID 22022581, 2011). "To evaluate the relationship of p44 with AR and ER in ovarian cancer, we first examined the expression levels of these receptors in the selected ovarian cell lines." (PMID 22022581, 2011). "Our data also indicated that AR and ER play a role in regulation of the nuclear-cytoplasmic translocation of p44 in ovarian cancer and subsequently cancer cell growth and invasion." (PMID 22022581, 2011). "Most ovarian carcinomas, including serous and endometrioid types, display varied levels of ER, PR, and AR expression." (PMID 22022581, 2011). "Increased levels of AR mRNA have been described in cells from normal ovarian surface epithelium as compared to ovarian cancer cells, the majority of which were derived from serous tumors." (PMID 20565760, 2010). "The expression of Rab25 correlated positively with AR expression supporting its role as an androgen responsive gene in ovarian cancer." (PMID 19623182, 2009). "It is possible that effects observed on Rab25 expression are mediated by an indirect mechanism, perhaps through TGFβ receptors, which have been shown to interact with the AR in ovarian cancer." (PMID 19623182, 2009). "It is noteworthy that 20% of ovarian carcinomas were positive with immunoreactivity for AR in more than 10% nuclei." (PMID 17020615, 2006). "Expression of the androgen receptor (AR) has been demonstrated in ovarian cancers using ligand binding assays." (PMID 11953818, 2002). "As the relationship between AR and treatment response to anti-androgen/AR-antagonist therapies in ovarian cancers is still unknown and worthy of further investigation." (PMID 40392873, 2025). "We cautiously propose the evaluation of AR expression in ovarian cancer, particularly in specific tumor types that may lack expression of other hormone receptors or biomarkers." (PMID 40392873, 2025). "Together, our study suggests a novel dual-inhibitory mechanism of flutamide on the AR pathway (AR expression suppression in addition to direct androgen antagonism) and supports its chemopreventive potential in ovarian cancer, especially for HR patients with low miR-449 expression." (PMID 39622842, 2024). "Our findings that flutamide effectively normalized the elevated protein biomarkers in HR patients lend further support to the importance of androgen signaling and the potential role of AR as a functional biomarker in the initiation and progression of ovarian cancer." (PMID 39622842, 2024). "In contrast, androgen receptor expression and action vary across ovarian cancer subtypes." (PMID 38994724, 2024). "Noradrenaline, adrenaline, and the nonspecific β-AR agonist, isoproterenol, were found to result in a significant increase in VEGF production by ovarian cancer cell lines, an effect blocked by cell treatment with the β1/2-AR antagonist, propranolol, indicating the involvement of β-AR in the process." (PMID 38067204, 2023). "Hence, we investigated the expression of SHRs and their clinical significance in patients with ovarian cancer and reported that the expression of the GR modifies the role of the progesterone receptor (PR) and affects the androgen receptor (AR)." (PMID 36969037, 2023). "The interaction of Nanog (a stemness marker gene) with the AR signaling axis can activate Nanog promoter transcription, which may induce or contribute to ovarian cancer stem cells (OCSCs) proliferation, migration, spheroid formation and colony formation." (PMID 35886904, 2022). "Excess androgens may directly affect ovarian cancer development through androgen receptor signaling." (PMID 36477251, 2022). "Therefore, selected high AR+ patients with ovarian cancer and the more potent AR antagonist enzalutamide achieved good safety and efficacy." (PMID 35886904, 2022).
ovarian carcinoma (continued). "Moreover, the expression of AR, ER, and PR among different subtypes of ovarian cancer varies significantly." (PMID 33891016, 2021). "AR can act as either an oncogene or a tumor suppressor in ovarian cancer." (PMID 33891016, 2021). "In addition, numerous studies have consistently revealed that the AR is overexpressed in ovarian cancer cells compared to normal ovary cells." (PMID 33613770, 2021). "AR was reported to mediate taxol resistance and affect survival of ovarian cancer." (PMID 33891016, 2021). "In contrast with breast cancer and prostate cancer, wherein the therapeutic and prognostic roles of AR, ER, and PR are already well established, the prognostic and predictive values of hormone receptors in ovarian cancer are inconsistent and sometimes contradictory." (PMID 33891016, 2021). "The semiquantitative analysis of the AR expression in the tissue microarray chips was performed by TissueQuest software (TissueGnostics) and the result suggested that the AR protein expression level in the ovarian cancer tissues was significantly higher compared to the para-cancerous tissues." (PMID 33613770, 2021). "CORAL represents the first trial of an AR targeted agent in ovarian cancer." (PMID 33854564, 2020). "The importance of AR in ovarian cancer has been previously explored." (PMID 32718331, 2020). "In addition, western blotting showed AR expression in 69% of human serous carcinoma cases as well as in the OVCAR-3 human ovarian cancer cell line." (PMID 30791431, 2019). "Interestingly, the androgen receptor (AR) is more widely expressed in ovarian cancer than either ER or PR, in up to 85% of cancers." (PMID 34926721, 2019). "Similarly, androgens increase the expression levels of AR and facilitate its nuclear translocation in ovarian cancer cells." (PMID 30791431, 2019). "We used a panel of AR-expressing ovarian cancer cell lines to test whether AR expression and activity lead to androgen-dependent growth of these cells." (PMID 34926721, 2019). "One or several of these genes may be more strongly regulated by transcription factors other than AR in ovarian cancer." (PMID 34926721, 2019). "The limited assessment of genetic susceptibility among AA is in modest sized study populations of candidate genes including the repeat polymorphisms of the androgen receptor (AR), vitamin D receptor (VDR) and cellular transport genes, where an association with risk of ovarian cancer was observed." (PMID 31001917, 2019). "AR expression has been confirmed in both normal ovarian tissues and ovarian carcinomas." (PMID 30791431, 2019). "It is possible that the same reciprocal relationship exists in ovarian cancer and that a similar combination treatment with an AR inhibitor, enzalutamide and a PI3K/AKT pathway inhibitor, metformin, could benefit ovarian cancer patients." (PMID 34926721, 2019). "Of these AR co-regulators, several have indeed been assessed in ovarian cancer tissue specimens and/or cell lines, although their functional role in AR activity or tumor growth remains largely unknown in ovarian cancer." (PMID 30791431, 2019). "Finally, we investigated the interaction between the PI3K/AKT and AR pathways in ovarian cancer cell lines treated with metformin and enzalutamide." (PMID 34926721, 2019). "Our study also provides a perspective therapeutic insight, specifically that the degradation of AR could provide the most effective therapeutic strategy for treating AR-positive serous subtype ovarian cancers." (PMID 30986993, 2019). "To investigate whether the Nanog-regulated stemness properties and tumorigenicity of the ovarian cancer cells were regulated by the AR signaling axis, we treated the A2780 + 20 and SKOV3 + 5 cell lines with DHT and performed sphere and colony formation assays." (PMID 29716628, 2018). "We also confirmed that AR and Nanog were co-localized in ovarian cancer cells." (PMID 29716628, 2018).
ovarian carcinoma (continued). "In this study, we investigated the interaction of Nanog with AR and examined whether this interaction induced stem-like properties in ovarian cancer cells." (PMID 29716628, 2018). "Furthermore, we found that the GFP signals were co-localized with the AR expression signals in the GFP (+) ovarian cancer cells." (PMID 29716628, 2018). "Moreover, to explore the possible regulation of AR and Nanog in ovarian cancer cells, the proliferation and migration abilities of single-clone Nanog GFP (+) cells with or without hormone treatments were examined." (PMID 29716628, 2018). "In conclusion, this study demonstrates that AR functions as an oncogene by promoting Nanog expression in ovarian cancer cells, and the interaction of Nanog with the AR signaling axis might induce or contribute to OCSC regulation." (PMID 29716628, 2018). "Thus, our in vitro studies showed that androgen induces Nanog-mediated stemness properties and tumorgenicity in ovarian cancer cells directly through AR." (PMID 29716628, 2018). "We further confirmed AR overexpression in ovarian cancer via immunohistochemistry." (PMID 29716628, 2018). "Shorter AR CAG repeats length and increased AR activity predict a high risk of ovarian cancer." (PMID 27741511, 2017). "In 1998, Risch hypothesized that epithelial ovarian cancers may develop as a result of androgens stimulating epithelial cell proliferation, and as it stands, a number of lines of evidence support the role for AR-signaling in the pathogenesis of the disease." (PMID 28085048, 2017). "A large body of evidence has consistently vindicated over-expression of AR in ovarian cancers." (PMID 27741511, 2017). "Accordingly, activation of AR may stimulate ovarian cancer cell migration and invasion resulting in a more aggressive phenotype." (PMID 27741511, 2017). "Some investigations sought to determine whether AR is divergently expressed in different histological subtypes of ovarian cancers." (PMID 27741511, 2017). "Our observations further support the idea that AR might function as a tumor promoter in ovarian cancer." (PMID 27741511, 2017). "Androgen receptor is frequently expressed in various subtypes of ovarian cancers and androgen/AR signaling has been shown to promote proliferation, migration, and invasion of ovarian cancer cells." (PMID 27741511, 2017). "Increased AR expression likely predicts a favorable prognosis in epithelial ovarian cancer." (PMID 27741511, 2017). "Notably, AR is the only hormone receptor included in the five good-prognosis predictors of the protein-driven index of ovarian cancer (PROVAR), a protein-based panel able to predict time to EOC recurrence." (PMID 28467804, 2017). "Similarly, a phase II study of enzalutamide, an androgen receptor inhibitor, in patients with recurrent AR + ve ovarian cancer is currently recruiting patients (NCT01974765)." (PMID 28666422, 2017). "Short (CAG)n repeat lengths in AR, altered expression and activity of AR co-activators, and/or differential expression of androgen-mediated genes likely also influence cancer biology and clinical outcome in ovarian epithelial cancer cells." (PMID 26318424, 2015). "Nevertheless, the nuclear fraction of AR was significantly reduced following inhibition of the AKT pathway in ovarian cancer cells, an observation which may be due to another cellular signal." (PMID 26318424, 2015). "Additionally, reports of transsexuals who developed ovarian cancer in the setting of androgen supplementation suggest a carcinogenic role for AR [S102]." (PMID 25595907, 2015). "High AR expression in 18% (28/154) of epithelial ovarian cancer was reported [S101]." (PMID 25595907, 2015). "Clinical trials with AR antagonists in ovarian cancer performed over 20 years ago suggested that only a small subset of tumours may respond to these drugs." (PMID 25608477, 2014). "AR is a prevalent sex steroid receptor expressed in ovarian cancers." (PMID 22022581, 2011).
ovarian carcinoma (continued). "In this study, the prognostic impact of AR expression was investigated using immunohistochemistry in tissue microarrays from 154 incident cases of epithelial ovarian cancer (EOC) in the prospective, population-based cohorts Malmö Diet and Cancer Study and Malmö Preventive Project." (PMID 20565760, 2010). "Altered androgen hormone homeostasis and androgen receptor (AR) activity have been implicated in ovarian carcinogenesis but the relationship between AR expression in ovarian cancer and clinical outcome remains unclear." (PMID 20565760, 2010). "Further work is required to investigate the functional role of Rab35 in ovarian cancer, but this gene may have use as a biomarker of AR function in ovarian cancer, thus being able to predict those patients who are likely to respond to antiandrogen therapy." (PMID 19623182, 2009). "We have previously shown that OSE cells express the AR and respond to androgen stimulation resulting in increased proliferation and protection from apoptosis, others have shown that the majority of ovarian cancers continue to express the AR." (PMID 19623182, 2009). "A significant number of ovarian carcinomas are also positive for AR." (PMID 17020615, 2006). "Further studies have shown AR to be expressed by as many as 90% of epithelial ovarian cancers." (PMID 11953818, 2002). "At the outset, based on the results of this study, it appears that androgen receptor is expressed at high rates and high intensities in the major types of ovarian cancers with the exception of clear cell carcinoma of the ovary supporting its potential as a target for therapy in ovarian cancer." (PMID 40392873, 2025). "While we found certain tumors to show strong or high rates of AR expression by immunohistochemical staining, the functionality of this hormone receptor in the ovarian cancers remains unknown; we have yet to determine if increased androgen exposure is a driver in tumor progression." (PMID 40392873, 2025). "However, in ovarian cancers, STS may be associated with more aggressive forms of OC while androgens and the AR may have distinct action in different subtypes of OC." (PMID 38994724, 2024). "Furthermore, KDM1A acts as a coregulator for hormone receptors (AR, ER, GR, MR) and may control ERβ expression in ovarian cancer (OCa)." (PMID 39239542, 2024). "Moreover, AR expression reduces patient survival whenever the protective effect of MMP-2 in the tumor stroma was absent; therefore, a deleterious effect mediated by AR associated to MMPs should be considered in ovarian cancer studies." (PMID 32718331, 2020). "Thus, AR overexpression likely correlates with resistance to paclitaxel in ovarian cancer cells." (PMID 30791431, 2019). "Thus, AR activity appears to positively correlate with the progression of ovarian cancer." (PMID 30791431, 2019). "Moreover, we investigated whether the AR protein co-localized with the Nanog protein in ovarian cancer cells." (PMID 29716628, 2018). "Therefore, our results indicated that AR and Nanog are co-localized in ovarian cancer cells." (PMID 29716628, 2018). "Therefore, in this study, we conducted an investigation to determine whether the AR signaling axis regulates Nanog and promotes stem-like differentiation and proliferation in ovarian cancer cells." (PMID 29716628, 2018). "We wondered whether a direct relationship existed between AR and Nanog in ovarian cancer." (PMID 29716628, 2018). "The authors detected that increased GGN(n) repeat reduced the risk of ovarian cancer, but at the same time, another previous population-based study from North Carolina did not detect any relationship between the GGC repeat length polymorphisms of the AR gene and the risk of ovarian cancer." (PMID 27741511, 2017). "Thus, we suspect that Androgen/AR signaling may promote ovarian cancer progression in part by decreasing TGF-beta receptor levels, thereby allowing ovarian cancer cells to escape TGF-beta growth inhibition." (PMID 27741511, 2017).